ZEB1 (zinc finger E-box binding homeobox 1)
Diseases named in the same sentence as ZEB1 in open-access papers (continued):
Sharing a sentence is not in itself a finding about the gene and the disease.
lung carcinoma (240 papers, 2009 to 2026). "It was also found that the epithelial–mesenchymal transition is associated with an elevated expression of ZEB1, which correlates with different grades and stages of lung cancer." (PMID 39770330, 2024). "In our study, we also observed the migration activity was impaired in MTHFD2-deficient lung cancer cells by affecting gene and protein expression of Zeb1, Vimentin and Snail." (PMID 35790743, 2022). "Dysregulation of Zeb1 and Zeb1-controlled cellular processes are tightly associated with formation and progression of different cancer types including breast and lung cancers." (PMID 36517518, 2022). "High autophagy activity (high ATG5 expression) and high Zeb1 expression are correlated and associated with poor clinical outcomes in human lung cancer." (PMID 33468994, 2021). "An EMT-independent mechanism for the biological functions of ZEB1 has also been reported in epidermal growth factor receptor (EGFR)-mutated lung cancer cells." (PMID 33097763, 2020). "The inactivation of LKB1, which is frequently mutated in lung adenocarcinomas, induces EMT in lung cancer cells through activation of ZEB1, whereas CHK1 mediates DNA damage response as part of EMT by stabilizing ZEB1." (PMID 29293502, 2018). "A study in lung cancer found a genetic context to the dual effects of ZEB1 with ZEB1 serving as an oncogene in KRAS-mutated lung cancer but as a tumor suppressor in EGFR-mutated lung cancer cells." (PMID 32309604, 2018). "Among the well-known EMT promoting transcription factors, ZEB1 has been uniquely correlated with loss of E-cadherin expression and anchorage-independent growth in human lung cancer cell lines." (PMID 29069783, 2017). "Whereas ZEB1 promoted growth in KRAS-mutated lung cancer cells, ZEB1 expression suppressed cell growth in EGFR-mutated lung cancer cells." (PMID 28587302, 2017). "Ectopic expression of ZEB1 in EGFR-mutated lung cancer cells inhibited cell growth by increasing miR-200c target Notch1, which repressed ErbB3 promoter activity and the expression of ErbB3." (PMID 28587302, 2017). "We recently reported that SLC2A3 encoding for GLUT3 is induced by ZEB1 during epithelial–mesenchymal transition (EMT) in tumor cells from non‐small cell lung cancer (NSCLC) and HCC." (PMID 28923827, 2017). "ZEB1 was recently implicated in pathological angiogenesis in lung cancer, although its exact mechanism of action is yet to be determined." (PMID 26882471, 2016). "ZEB1 is a driver of epithelial-to-mesenchymal transition that usually promotes lung cancer in the context of KRAS mutation." (PMID 27456471, 2016). "As such, our findings that ZEB1 distinctly regulates (promotes or suppresses) the growth of lung cancer cells harbouring KRAS or EGFR mutations is an important new observation." (PMID 27456471, 2016). "Herein, we report an unexpected finding that ZEB1 plays an opposite role in EGFR-mutated lung cancer cells by acting as a suppressor of cell growth." (PMID 27456471, 2016). "Here we report that ZEB1 exerts the opposite effect in EGFR-mutated lung cancer cells, where it suppresses growth by increasing microRNA-200 targets to antagonize ERBB3, a driver of mutant EGFR-dependent cell growth." (PMID 27456471, 2016). "Based on the previous finding demonstrating the unique correlation of the transcription factor Zeb1 with loss of E-cadherin expression in human lung cancer cell lines, here we only examined the role of Zeb1 on the observed TLE1-mediated E-cadherin repression." (PMID 27655370, 2016). "Along with miR-205, this family inhibits epithelial mesenchymal transition by targeting ZEB1 and ZEB2; in lung cancer miR-200c overexpression causes a reduced expression of ZEB1 and derepression of E-cadherin, the trascriptional target of ZEB1." (PMID 25593996, 2014). "Previously, we and others found that ZEB1 was predominantly responsible for the loss of E-cadherin in lung cancer cell lines." (PMID 24216980, 2013).
lung carcinoma (continued). "Moreover, ZEB1 represses HER3 promoter activity by suppressing NOTCH1 in EGFR-mutated lung cancer cells." (PMID 35042943, 2022). "Additionally, miR-200 family members suppress EMT, migration, invasion, and metastasis of lung cancer cells by directly repressing ZEB1, a gene encoding an EMT-inducing transcription factor." (PMID 32674274, 2020). "However, in the late and metastatic stages of lung cancer, expression profiles are changed in favor of ZEB1, which is associated with a decreased level of AGR2." (PMID 32570918, 2020). "Notably, human lung carcinoma cells resistant to docetaxel possessed significantly increased expression of ZEB1, while other transcriptional factors associated with EMT, including Snail, Twist, and Slug, were not deregulated." (PMID 32266287, 2020). "Hence, understanding how ZEB1 functions provides promise for innovative therapeutic strategies to improve lung cancer patient outcome, which remains the leading cause of cancer related death." (PMID 31719531, 2019). "Diffuse expression of ZEB1 is associated with poor survival rates in lung cancer patients." (PMID 26320193, 2015). "Targeting specific genes (such as SNAI1, ZEB1, miR-193A-3p, miR-210-3p, etc.)in these tumor-associated exosomes can effectively inhibit the exosome pathway to promote lung cancer metastasis, which may provide a new method for the prevention and treatment of lung cancer metastasis." (PMID 34511114, 2021). "In mice, miR-200b promotes LH secretion by targeting transcriptional repressor ZEB1 (zinc finger E-box binding homeobox 1), which is associated with aggressive behaviour, metastasis, treatment resistance and poor prognosis in different tumour types, including breast, pancreatic and lung cancer." (PMID 32121341, 2020). "Notably, ZEB1 downregulation was associated to a more invasive phenotype in lung cancer, suggesting that ZEB1-induced EMT and ESRP1-mediated splicing of CD44 could contribute to initial transitions of the metastatic progression." (PMID 28137272, 2017). "The mRNA levels of Itih2 and Zeb1 were markedly higher in mesenchymal-like lung cancer cells than in epithelial-like cells, with a positive correlation observed between their expression levels in all 13 murine lung cancer cell lines." (PMID 40178908, 2025). "Both ITIH2 and ZEB1 protein levels were elevated in mesenchymal-like lung cancer cells compared with their epithelial-like counterparts." (PMID 40178908, 2025). "Within the HA synthase family, Has2 exhibited the highest expression and proved to be under the regulatory influence of ZEB1 in murine lung cancer cells." (PMID 40178908, 2025). "studies demonstrate APOE-mediated angiogenesis via VEGF upregulation in bladder cancer, while lung cancer research reveals its EMT-inducing capacity through ZEB1/vimentin axis activation." (PMID 41390817, 2025). "They revealed that lung cancer cells exhibited cytoplasmic Zeb1, which maintained an epithelial expression pattern by interrupting actin cytoskeletal assembly." (PMID 40396518, 2025). "Lung cancer cells expressing high levels of ZEB1 secreted more ITIH2 compared with cells with low ZEB1 expression." (PMID 40178908, 2025). "For example, the systemic delivery of miR-200c, which negatively regulates the EMT master regulator ZEB1, enhances radiosensitivity in a lung cancer xenograft model." (PMID 40978098, 2025). "The 344SQ cell line, mesenchymal-like cells with high ZEB1 expression, was used to study lung cancer progression and metastasis in 129/Sv syngeneic mice." (PMID 40178908, 2025). "Immunoblot analysis also shows that TGF‐β‐induced upregulation of EMT‐associated molecules, including N‐cadherin, Snail, Twist1, and ZEB1, was abrogated by ProT overexpression in A549 and H1299 human lung cancer cells." (PMID 40259641, 2025). "The binding of ZEB1 to the FBP1 promoter was reported to increases DNA methylation in lung cancer cells." (PMID 40100307, 2025).
lung carcinoma (continued). "ZEB1 has also been reported to be negatively correlated with overall survival in patients with lung cancer." (PMID 40178908, 2025). "Overexpression of ZEB1 in epithelial-like 393P cells and HCC827 cells upregulated ITIH2 mRNA expression, while ZEB1 depletion in 344SQ murine lung cancer cells downregulated ITIH2 expression." (PMID 40178908, 2025). "Transforming growth factor-β increased the levels of ZEB1 and PD-L1 in both human and mouse lung cancer cells." (PMID 39343796, 2024). "Using GEPIA, we performed gene correlation analysis using Transcripts Per Million (TPM) for lung cancer data in the TCGA/GTEx database and found that the ZEB1 gene was positively correlated with the FBXO11 gene." (PMID 39409891, 2024). "ZEB1 expression levels have been shown to be correlated with EMT pathway activation in lung cancer tissues, suggesting the crucial role of CIB2/ZEB1 in tumor metastasis." (PMID 39264588, 2024). "Smoky coals induced down-regulation of miR-144, associated with increased Zeb1 expression and EMT phenotype in lung cancer." (PMID 39440184, 2024). "Tobacco induce down-regulation of miR-144, affecting Zeb1 expression and promoting epithelial-mesenchymal transition in lung cancer cells." (PMID 39440184, 2024). "Collectively, our study demonstrates that FBXO11 modulates EMT by mediating the stability of ZEB1 in lung cancer cells." (PMID 39409891, 2024). "Loss of FBXO11 increases ZEB1 levels, enhancing the invasiveness of lung cancer cells, while its overexpression reduces ZEB1 and suppresses invasion." (PMID 39409891, 2024). "This contrasts with A549 lung cancer cells, which constitutively express higher levels of Zeb1, and in which SCD inhibition already has a pro-ferroptotic effect without TGFβ stimulation." (PMID 39009641, 2024). "Previous studies have shown that GLUT3 is considered a transcriptional target of ZEB1, playing a significant role in lung cancer when tumour cells lose their epithelial features and become more aggressive, promoting lung cancer metastasis." (PMID 38594707, 2024). "This study systematically investigated the molecular mechanisms through which E3 ubiquitin ligase FBXO11 mediates the ubiquitination and degradation of ZEB1, thereby regulating the invasive metastasis of lung cancer cells." (PMID 39409891, 2024). "The transcription factor ZEB1 has an important role in altering the expression of epithelial genes in lung cancer, including SEMA3F." (PMID 39770330, 2024). "To clarify the major molecular mechanism by which CIB2 increases gefitinib resistance, we demonstrated that raised CIB2 in lung cancer cells promoted epithelial-to-mesenchymal transition (EMT) through upregulation of ZEB1." (PMID 39264588, 2024). "In lung cancer cell lines, ZEB1 is inversely correlated with E-cadherin expression and facilitates anchorage-independent colony formation." (PMID 36376711, 2023). "Their study also revealed that miR‐200 and ZEB1 can affect the migration ability of mesenchymal lung cancer cells in vitro through direct regulation of LOX proteins." (PMID 36684109, 2023). "In lung cancer and other tumor types, the prometastatic activity of zinc finger E-box–binding homeobox 1 (ZEB1) resides largely in its capacity to silence miR-200, miR-182/-183, miR-34a, and miR-148a." (PMID 36757799, 2023). "Given that PI4K2A localizes in endosomes and facilitates endosomal trafficking, we assessed PI4K2A as a mediator of ZEB1-dependent endosomal recycling, which has been shown to establish a polarity axis in lung cancer cells." (PMID 36757799, 2023). "Exosomal LINC00963 of lung cancer cells enhances the metastatic potential of lung cancer cells by decreasing the expression of seven in absentia homolog 1 (SIAH1) while increasing the zinc finger E-box-binding homeobox 1 (ZEB1) expression level." (PMID 37242707, 2023). "PNO1/CRISPR/Cas9 inhibited the mRNA and protein expression of Snail, Slug, and Zeb1 in lung cancer A549 and H460 cells." (PMID 36625087, 2023).
lung carcinoma (continued). "The influence of ZEB1 expression in immune infiltration has been well studied, with reports on the inhibition of immune response exerted by this protein in melanoma and lung cancer." (PMID 38093305, 2023). "PHRF1 binds to the proximal region adjacent to the transcription start site of ZEB1 and promotes the expression of Zeb1 and cell invasion in lung cancer A549 cells." (PMID 37540725, 2023). "Mice lung cancer cells treated with compound 6b inhibited the expression of the Twist and Zeb1 genes, which are responsible for EMT, leading to metastasis of tumor cells." (PMID 36080307, 2022). "We postulated that Itga1-mediated collagen adherence is required for ZEB1-driven lung cancer progression." (PMID 34874914, 2022). "The recent publication demonstrates that hypoxia-induced ZEB1 is involved in EGFR inhibitor resistance in lung cancer." (PMID 35798695, 2022). "Our results herein demonstrated that overexpression of HORMAD1 significantly increased the expression of ZEB-1, N-cadherin, and Vimentin and decreased the expression of E-cadherin in lung cancer cells." (PMID 35347116, 2022). "Chiu et.al reported that ERK promoted the expression of ZEB1 in pemetrexed resistant lung cancer cells." (PMID 36522730, 2022). "Studies have shown that H19 is highly expressed in lung cancer tissues and cell lines, promotes lung cancer cell growth, migration, and invasion, and upregulates the expression of ZEB1 and ZEB2 to further promote EMT." (PMID 36686745, 2022). "For example, Twist1 and ZEB1 were reported to be respectively overexpressed and downregulated in lung cancer." (PMID 35601657, 2022). "In another study, the miR-200/ZEB1 regulatory axis controls PD-L1 expression and metastasis of lung cancer cells in a Kras-driven oncogenesis model." (PMID 36248881, 2022). "In contrast, exposing cells to hypoxia has been shown to increase EMT-promoting transcription factors such as ZEB1 and have been implicated in driving EMT in lung cancer." (PMID 35932303, 2022). "In the process of bone metastasis of lung cancer, ZEB1, as the downstream target of Wnt/β-catenin, leads to the decrease of E-cadherin expression, which further aggravates EMT." (PMID 35483343, 2022). "For example, ZEB1 formed complex with NuRD contributing to the degradation of E-cadherin, thus promoting metastasis in lung cancer." (PMID 34409034, 2021). "Enhanced stemness of human lung CSCs by Zeb1 is consistent with our previous study conducted using the mouse Lewis lung cancer cells." (PMID 33468994, 2021). "The promoter region of p21 was subcloned upstream of a luciferase reporter and transfected into human lung cancer cells with either ZEB1 or miR-200 expression." (PMID 34309585, 2021). "Alternative splicing events associated with EMT have been recently explored by induction of the EMT promoting factor ZEB1 in lung carcinoma H358 cells." (PMID 34009296, 2021). "Through analyzing the TCGA database via the Gene Expression Profiling Interactive Analysis (GEPIA), we found that the expression of STAT3 were correlated with ZEB1 in both lung cancer tissues and normal tissues." (PMID 34059647, 2021). "The wound healing and transwell data demonstrated that silencing ZEB1 inhibits the invasion and migration of gefitinib-resistant lung cancer cells." (PMID 34059647, 2021). "Recent studies revealed that ZEB1 contributes to the EMT‐mediated acquired resistance to gefitinib in EGFR‐mutant non‐small cell lung cancer (NSCLC)." (PMID 33764690, 2021). "Here we highlight the unreported details of PHRF1 in the invasion of lung cancer cells by modulating the transcriptional level of ZEB1, a prominent regulator involved in epithelial-mesenchymal transition." (PMID 32730336, 2020). "It has been reported that EMT-associated transcriptional factors, including Twist1, Snail, Slug and ZEB1, play a critical role in lung cancer stemness." (PMID 32549341, 2020).
lung carcinoma (continued). "Similar results were observed in human lung cancer cells, where ZEB1 overexpression enhanced both miR-374a and miR-374b expression in HCC827 cells, and use of the miR-200b mimic suppressed the expression of these miRNAs in A549 cells." (PMID 32674274, 2020). "For example, in lung cancer cells, ZEB1 was shown to downregulate ESRP1 expression through direct binding to its promoter, contributing to a positive loop fostering EMT." (PMID 33158935, 2020). "Further, we saw high expression in EC cells of ZEB1, which is proved to be an oncogene in various cancers, including colorectal cancer and lung cancer, as well as ESCC." (PMID 33292221, 2020). "In lung cancer cells, hsa-circ-0023404 decreases the expression of miR-217 to enhance the expression of its target, ZEB1, leading to the increased migration and invasion of cancer cells." (PMID 32664703, 2020). "To clarify the association between miR-374a/b and EMT, we measured levels of miR-374a and miR-374b in murine lung cancer cells in which EMT status had been manipulated by ZEB1 and miR-200." (PMID 32674274, 2020). "High ZEB1 expression has been recognized in various human malignances, for example the lung cancer and hepatocellular carcinoma." (PMID 32667627, 2020). "Some circRNAs like circ-ZEB1.19, circZEB-1.17, circZEB1.5, and circZEB1.33 suppress lung cancer progression by acting as miR-200 sponge target for ZEB1." (PMID 32467674, 2020). "In contrast, our data clearly demonstrate that AGR2 expression is suppressed by ZEB1 expression in lung cancer cells." (PMID 32570918, 2020). "Our data revealed that, among the classic EMT-associated transcription factors (SNAI1 and ZEB1/2), PHRF1 substantially regulates the expression of ZEB1/2 and is required for the initiation of the EMT process in lung cancer cells." (PMID 32730336, 2020). "Together, our findings cement a novel link of PHRF1 with ZEB1 in the process of lung cancer metastasis." (PMID 32730336, 2020). "In lung cancer cell lines, ZEB1 is inversely correlated with expression of E-cadherin and promotes anchorage-independent colony formation." (PMID 32730336, 2020). "By targeting zinc finger E-box binding homeobox 1 (ZEB1), miR-144 can limit the proliferative capacity of lung cancer cells." (PMID 33046994, 2020). "For instance, ZEB1 represents the direct downstream target of Wnt-activated beta-catenin in bone metastasis of lung cancer, resulting in decreased levels of E-cadherin and EMT." (PMID 32266287, 2020). "We previously found that miR-34a is negatively correlated with Zeb1 mRNA and positively correlated with miR-200 family members in lung adenocarcinoma data from TCGA and lung cancer cells." (PMID 30700696, 2019). "An additional study using a model of pemetrexed-resistant lung cancer cells showed that ERK1/2 contributed to the induction of ZEB1 and fibronectin while decreasing the expression of E-cadherin, therefore inducing EMT." (PMID 31200510, 2019). "The dysregulation of ZEB1 expression is associated with poor clinical prognosis in numerous epithelial cancers and notably drives EMT in lung cancer pathogenesis." (PMID 31719531, 2019). "Reduced miR-200 and enhanced ZEB1 expression in lung cancer cells not only can evoke EMT, but also can lead to enhanced expression of PD-L1, which is related to the exhaustion of CD8+ T lymphocytes in lung cancer tissues." (PMID 31766574, 2019). "In epithelial-like 393P murine lung cancer cells, the ectopic expression of Zeb1 suppressed miR-34a, while it slightly increased miR-34b/c expression." (PMID 30700696, 2019). "A lung cancer study showed that PD-L1 is a downstream target of the interaction between ZEB1 and miR-200, which suppress each other." (PMID 29732001, 2018). "Zeb1 was shown to promote the progression of lung cancer by increasing the expression of MMP2, a member of the matrix metalloproteinases family that play an important role in cell migration and facilitate invasion and metastasis of tumor cells." (PMID 30580326, 2018).